GAPDH (glyceraldehyde-3-phosphate dehydrogenase)
Diseases named in the same sentence as GAPDH in open-access papers (continued):
Sharing a sentence is not in itself a finding about the gene and the disease.
cancer (continued). "Since most cancers have evolved multiple strategies such as hypoxia to evade programmed cell death, it is suggested that GAPDH-dependent Akt expression is protecting cancer cells from hypoxia." (PMID 26508976, 2015). "Excellent reviews are already published on the various GAPDH functions with increasing knowledge on either neurodegenerative diseases or cancer implication." (PMID 26556350, 2015). "One of the most common effects of GAPDH is its inconsistent role in the determination of cancer cell fate." (PMID 25859407, 2015). "Remarkably increased GAPDH levels are observed in many human cancer types and often correlated with reduced survival." (PMID 25859407, 2015). "GAPDH gene is stably and constitutively expressed at high expression levels in cancer cells and is used as a housekeeping gene." (PMID 25951128, 2015). "Partial inhibition of GAPDH expression in mammalian cells by small interference RNA resulted in the rapid shortening of telomeres, whereas the overexpression of nuclear GAPDH resulted in the protection of telomeric DNA in response to anti-cancer drugs." (PMID 25775131, 2015). "In cancer, the interaction of GAPDH to telomers leads to chemoresistance and apoptosis or senescence." (PMID 26556350, 2015). "In this study we have found that Hs738 gastric stromal cells secrete IL-6 and GAPDH for positive and negative regulation of cancer cells, respectively." (PMID 25785838, 2015). "Mechanisms and pathways involved in GAPDH regulation and its different roles in cancer cells are also described." (PMID 25859407, 2015). "The ratio of β-F1-ATPase to HSP60 (mitochondrial) relative to GAPDH (glycolytic potential) has been shown to be associated with patient survival suggesting that mitochondrial oncobioenergetic functional profile may be a useful parameter to predict the aggressiveness of cancer." (PMID 26515588, 2015). "for human colorectal normal and cancer tissues as individual data points using the 2-ΔCt [2-(Ct NALP1-Ct GAPDH)]." (PMID 25611377, 2015). "Overexpression of GAPDH has been reported in cancers, and the primary role for GAPDH was proposed to be its pivotal function in glycolysis." (PMID 24527027, 2014). "They identified several proteins that were hyper-O-GlcNAcylated in cancer tissues; among them, four were glycolytic enzymes: enolase 2, triosephosphate isomerase, PK, and glyceraldehyde 3-phosphate dehydrogenase (GAPDH)." (PMID 24918087, 2014). "After quantification of ZFP91 abundance in cells using GAPDH levels as a reference, markedly higher protein quantity was noted in all cancer cell lines comparing to normal prostate epithelial cells (PrEC)." (PMID 24272675, 2014). "Other authors showed that GAPDH expression varies according to oxygen tension and hypoxia, critical factors in cancer development, especially in CRC." (PMID 24484585, 2014). "These particles proved to be efficiently internalized by cancer cells and selectively knockdown GAPDH and Bcl-2 expression at both the protein and mRNA levels." (PMID 25229941, 2014). "Current studies suggest that GAPDH is upregulated in many cancers and is the primary target of some chemotherapeutic drugs." (PMID 24367685, 2013). "The level of HDAC1 associated with the control promoter GAPDH was unchanged between cell lines, but was more than doubled at RGS10-1 promoters in the cancer cell line, compared to IOSE cells." (PMID 23533674, 2013). "The fact that GAPDH is over-expressed in cancer cells seems paradoxical since it was shown that GAPDH is able to prevent caspase-independent cell death by increasing the amount of intracellular ATP and by stimulating autophagy." (PMID 23476653, 2013). "In sum, our data suggest that GAPDH serves a key role in cell cycle regulation and cell senescence during cancer cell development." (PMID 23620736, 2013).
cancer (continued). "Gal-4 mRNA levels showed a relative low abundance in eight of the nine cancer cell lines, using GAPDH as a household reference gene." (PMID 23824659, 2013). "In order to trigger cell cycle related events, it is possible that both GAPDH and FoxM1 translocate from the cytoplasm to the nucleus in cancer cells." (PMID 23620736, 2013). "This suggests another mechanism by which increased GAPDH expression contributes to a survival advantage in cancer cells." (PMID 24367685, 2013). "From a therapeutic point of view given the central role of GAPDH, it is conceivable that, apart from blocking glycolysis and ATP production, GAPDH inhibition would result in multipronged effects within the cancer cell." (PMID 24298908, 2013). "In a recent review GAPDH expression was reported deregulated in e.g. cancers of the lung, breast, colon, pancreas, liver, kidney and prostate." (PMID 24252137, 2013). "In one possibly cancer-related scenario, GAPDH was found to be a pro-survival regulator of caspase-independent cell death (CICD)." (PMID 23620736, 2013). "Using a publically available microarray database, we identified a group of genes whose expression levels in some cancers are highly correlated with GAPDH up-regulation." (PMID 23620736, 2013). "Collectively, our data suggest that nanoliposomal C6-ceramide is targeting GAPDH and presents a new mechanism for which ceramide is selectively targeting cancer cells." (PMID 24367685, 2013). "Specifically, within the cancer cohort, 341 up-regulated genes were identified with a GAPDH expression correlation coefficient greater than or equal to 0.6." (PMID 23620736, 2013). "In contrast to the cancer tissues, analysis of the cancer-free control tissues in the cohort identified only 5/70 (7%) of the genes that correlated positively with GAPDH expression (r greater than or equal to 0.6)." (PMID 23620736, 2013). "By binding to GAPDH inside the cancer cells, 3-BrPA depletes ATP profoundly depriving the cancer cells of any energy." (PMID 24298908, 2013). "Several inhibitors derived from natural and / or synthetic sources have been investigated for their anti-GAPDH efficacy in treating cancer." (PMID 22964488, 2012). "The glycolytic enzyme, glyceraldehyde-3-phosphate dehydrogenase (GAPDH), a multifunctional protein primarily recognized for its role in glucose metabolism, has already been shown to affect the proliferative potential of cancer cells." (PMID 22964488, 2012). "In carcinoma samples the peptidyl-prolyl cis-trans isomerase A, ERp57, serpin B3, Annexin 2 and GAPDH were found less oxidized than in dysplastic tissues." (PMID 22470562, 2012). "The bioenergetic signature is a protein ratio (β-F1-ATPase/GAPDH), which provides an estimate of glucose metabolism in tumors and serves as a prognostic indicator for cancer patients." (PMID 21303518, 2011). "The expression of GAPDH was significantly decreased in a dose-dependent manner following amino-bisphosphophates treatment to the cancer cells." (PMID 20707929, 2010). "In contrast, Zhong & Simons (1999) showed GAPDH was increased in cancer cells under hypoxic conditions." (PMID 20707929, 2010). "RNA was successfully isolated from 134 carcinomas, all 14 benign breast tissue samples and 33 normal breast tissue samples, demonstrated by detection of GAPDH by manual PCR." (PMID 20678196, 2010). "Further confirmation was obtained by P2X7 mRNA experiments where qPCR assays revealed a five fold lower P2X7 mRNA/GAPDH mRNA levels in normal tissues than in cancer tissues." (PMID 19379509, 2009). "By using these procedures we found that among the ERα- positive tissues, the mean GPR30 mRNA expression levels relative to GAPDH levels were 0.0058 (SD = 0.0075) in normal tissues and 0.0026 (SD = 0.0038) in cancer tissues." (PMID 21655374, 2008).
cancer (continued). "The mean expression value of MCAK mRNA in cancer tissues was 0.25±0.015 (mean±s.d., normalised by GAPDH gene expression), which was significantly higher than the value of 0.18±0.025 in the corresponding non-malignant tissues (P=0.0145; Student's t-test)." (PMID 17653072, 2007). "The expression levels of CEACAM6 mRNA, which were corrected for those of GAPDH mRNA, in cancer tissues (5.90±8.74; mean±s.d)." (PMID 16868542, 2006). "Our results show a significant dose-dependent down-regulation of GAPDH gene expression after treatment of different cancer cell lines with different amino-BPs." (PMID 16515701, 2006). "The survivin/GAPDH ratio of carcinomas (mean±standard error (s.e.): 5.3±0.8, range: 0.4–37) was significantly higher than that of non-cancerous tissues (3.6±0.8, range: 0–37.5, P=0.0003)." (PMID 12373603, 2002). "In contrast, accumulating evidence suggests that GAPDH is a pan-cancer marker and an EC marker." (PMID 40943534, 2025). "Notably, several metabolic enzymes engaged in glycolysis, the primary energy-generating pathway in cancer cells, also serveas ncRBPs such as pyruvate Kinase M, aldolase A, phosphoglycerate kinase and GAPDH." (PMID 41175344, 2025). "Against GAPDH (1U8F), Nyctanthic acid also showed a competitive binding affinity (−113.841 kcal/mol) compared to β‐Glucogallin (−112.534) and Galuteolin (−117.778 kcal/mol), highlighting its comparable affinity toward this cancer‐related protein target." (PMID 40933552, 2025). "GAPDH, typically recognized as a housekeeping gene, might play oncogenic roles across various cancers." (PMID 40236649, 2025). "For instance, AKR1B10 may interact with glyceraldehyde-3-phosphate dehydrogenase to reduce autophagy by modifying its reductase activity in cancer cells." (PMID 39744163, 2025). "Similarly, GAPDH, beyond its role in glycolysis, is overexpressed in many cancers including OC, where it contributes to the Warburg effect, supports rapid energy production, and modulates apoptosis and gene transcription." (PMID 40933552, 2025). "Studies indicate that GAPDH may regulate cell proliferation and apoptosis, which are key processes in cancer development and progression." (PMID 40129771, 2025). "Additionally, the TISCH2 indicated that all the hub-genes of cancer cells were upregulated in malignant cells, especially GAPDH, RHOA, TPI1, H4C6, DDX21, and APEX1, which showed considerably high expression levels in malignant cells." (PMID 40906153, 2025). "The dependence of cancer cells on GAPDH due to the increased glucose consumption is well known." (PMID 41175344, 2025). "Inhibiting GAPDH can disrupt cancer metabolism and trigger apoptotic pathways." (PMID 40933552, 2025). "While widely employed for this purpose, GAPDH expression may be affected under certain cancer-related metabolic conditions, and its stability should be interpreted with caution." (PMID 40649712, 2025). "Furthermore, gene expression analyses revealed significant upregulation of caspase 9 and key alterations in cancer‐related genes, including Bcl‐2, Bax, and GAPDH, implicating the caspase 9‐mediated apoptotic pathway as a central mechanism of action." (PMID 40079412, 2025). "Indeed, a solid body of evidence demonstrates with diverse laboratory techniques that GAPDH mRNA levels vary among normal cells and different malignancies, cancer cell lines, as well as cancer tissue biopsies." (PMID 40943534, 2025). "Modulating specifically the stability and decay of GAPDH targets may be a promising cancer treatment strategy." (PMID 41175344, 2025). "The dual roles of GAPDH in cancer are a good example of its ability to control cell death pathways." (PMID 38611852, 2024). "This observed inhibition of GAPDH can trigger different scenarios in the cancer cells." (PMID 38512909, 2024). "The impact of GAPDH on cancer is primarily observed in two aspects." (PMID 39199428, 2024). "Also, a high level of glyceraldehyde-3-phosphate dehydrogenase (GAPDH) was found in various cancer types." (PMID 39201484, 2024).
cancer (continued). "It has been reported that GAPDH may play an oncogenic role in cancer through DNA copy number amplification, altered promoter methylation, and/or FOXM1-regulated overexpression." (PMID 39188753, 2024). "Energy metabolism is altered in many cancers and may be addressed with the use of antisense oligonucleotides or GAPDH-inhibitors such as fumaric acid esters." (PMID 38793784, 2024). "On one hand, GAPDH participates in the glycolytic process, providing essential energy and substrates for cellular activities such as the proliferation, invasion, and metastasis of cancer cells, ultimately promoting cancer growth." (PMID 39199428, 2024). "It has been reported that GAPDH is frequently dysregulated in numerous cancer types." (PMID 39596473, 2024). "Targeting glyceraldehyde‐3‐phosphate dehydrogenase (GAPDH) might be important in cancer therapy due to a decrease in ATP levels and inhibition of autophagy." (PMID 38919334, 2024). "To demonstrate the functionality of the PCAS, we conducted an analysis of GAPDH across multiple cancer types, revealing a significant upregulation of protein levels, which is consistent with its important biological and clinical significance in tumors, as indicated in our prior research." (PMID 38928396, 2024). "Cancer cells invading the lung mesenchyme were then measured using qPCR of human GAPDH gDNA." (PMID 38649663, 2024). "Here,a double-tagging RT-PCR on magnetic beads and electrochemical genosensingdemonstrated high sensitivity and specificity for GAPDH gene expressionbased on specific epithelial CD326 cancer-related exosomes, beingable to detect the transcripts produced by as low as 1225 exosomesμL–1." (PMID 36683335, 2023). "Furthermore, the LUAD-TCGA dataset showed a positive correlation between SLC7A5 and GAPDH mRNA expression in the cancer patient samples (r = 0.45, p = 1.55E−26)." (PMID 37095081, 2023). "Moreover, GAPDH protects cancer cells against chemotherapy by directly binding to the telomeric DNA and prevents the rapid degradation of telomeres." (PMID 36624663, 2023). "For instance, overexpressed GAPDH could inhibit caspase-independent cell death by inducing Bcl-xL upregulation, leading to cancer cell survival and resistance to chemotherapeutic agents." (PMID 36624663, 2023). "Besides its role in energy metabolism, GAPDH can also interfere with the cancer cells’ destiny, for which GAPDH is able to serve as a regulator of cell death." (PMID 35874525, 2022). "Therefore, the results further proved that GAPDH was suitable as a reference gene in the platelets for pan-cancer." (PMID 35770000, 2022). "GAPDH is a multi-functional protein with separate and antagonistic roles in cancer cell survival." (PMID 36267982, 2022). "Membrane GAPDH also acts as a plasminogen receptor in infiltrating macrophages, and it is intriguing to consider that cancer cells might utilize this function to promote invasion." (PMID 36267982, 2022). "However, it is also reported that GAPDH induces an arrest of telomere maintenance and the proliferation of cancer cells." (PMID 35804814, 2022). "The effect of sorafenib, bevacizumab, panitumumab, ramucirumab, sorafenib-bevacizumab, sorafenib-panitumumab and sorafenib-ramucirumab on the relative gene expression of CASPASE3, MMP-9, VEGFR2 and EGFR in HepG2 cancer cells was determined by RT-PCR using GAPDH as a normalizer." (PMID 36284117, 2022). "GAPDH promotes cancer growth and metastasis through upregulation of SNAIL expression." (PMID 35089096, 2022). "Finally, according to the analysis results from the website of the Platelet Expression Atlas, the expression of GAPDH in platelets was stable in a variety of cancers when compared with that in healthy subjects, including some uncommon cancers." (PMID 35770000, 2022).
cancer (continued). "The effect of sorafenib, bevacizumab, panitumumab, ramucirumab, sorafenib- bevacizumab, sorafenib-panitumumab and sorafenib-ramucirumab on the protein expression of cleaved CASPASE3, VEGFR2 and EGFR in HepG2 cancer cells was determined by western blot using GAPDH as a normalizer." (PMID 36284117, 2022). "Furthermore, the candidate reference genes were ranked in the increasing order of their stability values, and the GAPDH was the best reference gene in platelets for pan-cancer." (PMID 35770000, 2022). "Glyceraldehyde-3-phosphate dehydrogenase (GAPDH) is a pivotal enzyme, and it regulated cellular senescence phenotype in A549 cells via modulating the AMPK network, a key pathway implicated in cancer cell lipid metabolism." (PMID 35186082, 2022). "Given the relevance of both GAPDH and enolase activity in cancer, we are left to wait and wonder about whether and how Src phosphorylation might influence their role in cancer biology, as it has been clearly established for other glycolytic enzymes." (PMID 36217026, 2022). "In the images we obtained in the study, GAPDH is down-regulated in various cancer cells." (PMID 35874525, 2022). "At the same time, GAPDH was significantly higher in cancer tissues." (PMID 36358600, 2022). "Therefore, human-specific GAPDH qRT-PCR of purified RNA is comparable to Alu qPCR of purified DNA for detecting a few human cancer cells in abundant mouse tissue." (PMID 33575432, 2021). "Moreover, the effects on tetramerization result in a reduction in cytosolic GAPDH and tubulin expression which have a direct impact on the ability of cancer cells to invade and migrate." (PMID 34880756, 2021). "Thus, two consequences of hypoxia are likely to be deleterious for a cancer cell experiencing hypoxia, reduced efficiency of GAPDH in glycolysis and the Warburg effect and its aggregation due to increased expression of the enzyme and its denaturation." (PMID 33546324, 2021). "GAPDH has been shown to enhance mitophagy and induce cancer cell survival." (PMID 35004842, 2021). "Therefore, in cancer cells, Hsp70-mediated chaperoning of GAPDH becomes a promising target for antitumor therapy." (PMID 33546324, 2021). "Thirdly, the two cancer-associated CSB mutations R1467Q and G1484R, located on the opposite side of the CSB-WHD away from its ubiquitin-binding pocket, impair RNAPII association with PPP sites of ACTB, GAPDH and RPL13A genes." (PMID 33806087, 2021). "Furthermore, data were then normalized to β-Actin to avoid possible bias of different GAPDH expression which is known for different cancer cells." (PMID 34073147, 2021). "Moreover, the high activity of GAPDH increased the mobility of cancer cells, and epithelial–mesenchymal transition (EMT) markers are significantly associated." (PMID 34650911, 2021). "This analysis method that uses GAPDH as an internal reference may be unreliable due to the downregulation of GAPDH in cancer cells." (PMID 34034688, 2021). "GAPDH overexpression is involved in the processes where cancer cells hijack normal pathways." (PMID 34257558, 2021). "In contrast, GAPDH knockdown in cancer cells leads to cell death." (PMID 32098782, 2020). "Various non-glycolytic functions of GAPDH have been reported in cancer, such as, it has been reported that GAPDH overexpression in cell nucleus is associated with cell cycle via its effect on cyclin B-cdk1 activity." (PMID 32635458, 2020). "Genes associated with cancer stem cells and EMT markers could be optimally analyzed by normalizing them with GAPDH and PUM1 as housekeeping genes." (PMID 33457124, 2020). "The impact of GAPDH on the efficacy of metabolism in cancer cells may be also regulated by the coactivator-associated arginine methyltransferase 1 (CARM1 or PRMT4), an enzyme methylating arginine-234 on the GAPDH molecule." (PMID 32370188, 2020).